VDR (vitamin D receptor)
Diseases named in the same sentence as VDR in open-access papers (continued):
Sharing a sentence is not in itself a finding about the gene and the disease.
cancer (continued). "The inherited genetic variations in the VDR gene may contribute in part to susceptibility to cancer at a younger age." (PMID 30699973, 2019). "Vitamin D receptor (VDR) expression has been associated with survival in several cancer sites." (PMID 30344947, 2018). "These lines of evidence demonstrated that VDR may interact with 1,25(OH)2D to reduce the risk of cancer and play a potential antitumour role in the development and progression of cancer." (PMID 29659618, 2018). "Therefore, the associations of VDR polymorphisms with the risks of various diseases, including cancer and immune disease, have been extensively examined in epidemiologic studies." (PMID 30150667, 2018). "The VDR-related cancer risk appears to be tissue-specific as it varies in different cancers." (PMID 29951549, 2018). "It has been reported that 1,25(OH)2D/VDR can suppress NF-kB activities, resulting in decreased expression of proinflammatory cytokines and inhibition of cell proliferation and of cancer-associated inflammation, with slowing down cancer growth." (PMID 29951549, 2018). "Several polymorphisms have been identified in various introns and exons of VDR gene most commonly ApaI, BsmI and FokI, and recent studies have indicated that these SNPs may be linked with many kinds of cancer risks." (PMID 28380424, 2017). "Studies on VDR polymorphisms (BsmI, TaqI, FokI, and ApaI), and MAs on data from observational studies also support an association between low 25OHD levels and an increased risk of malignant diseases as well as cancer mortality." (PMID 28686645, 2017). "Several polymorphisms have been identified in various introns and exons of VDR gene, including ApaI, BsmI and FokI, and recent studies have indicated that these SNPs may be linked with many kinds of cancer risks." (PMID 28380424, 2017). "Significant associations with VDR polymorphisms have been reported for prostate (Fok1, Bsm1, and Taq1), breast (Fok1, Bsm1, and Apa1), colon-rectum (Fok1, Bsm1, and Taq1), and skin (Fok1, Bsm1, and Taq1) cancers." (PMID 28895880, 2017). "In particular, the fact that VDR b and T alleles are more frequent in cachectic cancer patients with elevated CRP levels leads to the conclusion that this may represent an early clinical predictor for more aggressive forms of cachexia." (PMID 28423519, 2017). "Recently, several genetic studies have demonstrated that an individual’s susceptibility to autoimmune disorders and cancers is associated with polymorphisms in numerous proteins and enzymes associated with vitamin D function, including VDR, DBP, CYP27B1, CYP2R1, and CYP24A1." (PMID 28895880, 2017). "The use of a single model cell line is a limitation of this study and it is currently unknown if cytoplasmic VDR accumulation causes similar effects in other cancer cell lines." (PMID 28460457, 2017). "Increased tumor VDR expression is associated with a better prognosis in various types of cancer." (PMID 28489590, 2017). "Vitamin D receptor (VDR) gene polymorphisms have been reported to increase susceptibility to some malignant tumors, yet the effect on gastric cardiac adenocarcinoma susceptibility remains unknown." (PMID 28489590, 2017). "Genetic variation in VDR could lead to vitamin D deficiency, which is associated with increased risk for cancer and a variety of other diseases." (PMID 29272316, 2017). "Epigenetic inactivation of human VDR, reducing its mRNA and protein expression, has been shown in various cancer types, supporting the loss of an antiproliferative role of VDR, and may potentially occur in ACCs." (PMID 26843863, 2015).
cancer (continued). "Although the majority of the physiological effects of VDR polymorphisms are not fully understood, it has been postulated that these polymorphisms may influence the risk of cancer occurrence." (PMID 25839036, 2015). "The role of vitamin D status in cancer risk has received strong experimental support from the consistent demonstration that activation of the vitamin D receptor (VDR) by locally produced calcitriol induces differentiation and apoptosis, and inhibits cell proliferation and angiogenesis." (PMID 25376735, 2014). "As VDR is rarely mutated during carcinogenesis, the disturbance of the vitamin D signaling and apparent 1,25-D3 insensitivity in cancer must be attributed to other alterations, which may include epigenetic changes, such as promoter methylation." (PMID 24808866, 2014). "It has been postulated that the VDR gene polymorphisms may influence both the risk of cancer occurrence and its prognosis." (PMID 24297042, 2014). "Effect modification may also have an effect on the link between the mediator (vitamin D) and the outcome (cancer), as is suggested by the different polymorphisms affecting the VDR." (PMID 25255691, 2014). "However cancer cells are often resistant to the antiproliferative and differentiating properties of vitamin D, as a result of the increased association of the VDR with corepressors on chromatine." (PMID 25546457, 2014). "VDR, an intracellular hormone receptor, is expressed in normal colon epithelial cells and other colon cells at various levels, and higher expression correlates with epithelial differentiation and better prognosis, while VDR downregulation is associated with poor prognosis and cancer progression." (PMID 25195132, 2014). "The loss of anti-proliferative responsiveness in cancer cells toward ligands for VDR, RXRs, and PPARs may require underlying epigenetic events." (PMID 24202445, 2013). "Moreover, deletion of the VDR gene in VDR−/− mice predisposes these mice to higher risk and susceptibility to chemically-induced cancers of the skin, prostate, blood, lymph and breast." (PMID 24084056, 2013). "These could be the underlying mechanisms for the cell-specific functions of 1α,25-(OH)2D and could lead to diverse associations between the VDR polymorphisms and the risk of cancer of different tissues." (PMID 23826116, 2013). "The VDR gene is located on chromosome 12q12–q14, and several single-nucleotide polymorphisms have been identified that may influence cancer risk." (PMID 23586065, 2013). "A complementary approach to testing the vitamin-D-cancer hypothesis is to study polymorphisms in the vitamin D receptor (VDR), a key mediator of vitamin D activity which is expressed in normal and malignant breast cells." (PMID 23533810, 2013). "It has been hypothesized that a less active VDR could be associated with either an increased susceptibility to cancer risk or to a more aggressive disease." (PMID 23586065, 2013). "Several studies have determined the contribution of VDR polymorphisms in various types of cancer." (PMID 23691496, 2013). "VDR expression rates were associated with KRAS mutation in several cancer types." (PMID 23691496, 2013). "Indeed, genetic heterogeneity effects of vitamin D signaling related genes, especially the VDR gene, have been attractive research subjects for cancer risk studies and potential applications in cancer prevention strategy." (PMID 21991434, 2011). "In conclusion, this meta-analysis showed that VDR FokI and BsmI polymorphisms may modulate the risk of cancer of the breast, skin and prostate and possibly affect cancer risk at any site in Caucasians." (PMID 22276021, 2009). "In addition to these dietary factors that modify cancer risk, BMI and age also appear to be ‘effect modifiers’ of the association between VDR and cancer." (PMID 22276021, 2009).
cancer (continued). "The characterization of these and other polymorphisms in the VDR gene may help to better understand the aetiology and development of cancer, and to define risk groups to better target prevention strategies." (PMID 19105801, 2008). "The possibility that SNAIL upregulation reported in melanoma, gastric or other cancers may also cause VDR downregulation in these neoplasias remains unexplored." (PMID 15770204, 2005). "However, vitamin D receptor activation in cancer-associated fibroblasts can eliminate CAF-derived IL-8 mediated GC oxaliplatin resistance in GC by blocking PI3K/Akt signaling, which provides a promising basis for overcoming GC drug resistance in clinical practice." (PMID 40485724, 2025). "In addition, specific VDR gene variants or polymorphisms may influence cancer incidence, severity, and mortality." (PMID 40732958, 2025). "Polymorphisms in the VDR may also influence associations between 25(OH)D and cancer survival." (PMID 37526780, 2024). "This first pan-cancer analysis of VDR indicates that VDR may serve as a prognostic biomarker and VDR is positively associated with immune infiltration as well as stromal or immune components in the tumor microenvironment in multiple human cancers." (PMID 38639057, 2024). "Furthermore, some VDR agonists (paricalcitol due to its normalization effect on stellate cells) are presently under investigation as a potential candidate for clinically targeting cancer-associated fibroblasts (CAFs)." (PMID 38360633, 2024). "The low level of LCA may lead to the normal activation of VDR through its natural ligand that has been associated with anti-proliferative effects in various cancer types by the control of cell cycle regulators, induction of apoptosis, and inhibition of angiogenesis." (PMID 37887360, 2023). "Thus, a first possibility is that the elimination of VDR could increase the susceptibility of the animals to develop some kind of cancer." (PMID 35406129, 2022). "Additionally, some VDR polymorphisms are associated with increased risk of developing cancer." (PMID 35662320, 2022). "Epidemiologic evidence supports the role of vitamin D and vitamin D receptor (VDR) polymorphisms in the risk of several cancers, 1,25(OH)2D affecting cell differentiation and growth, as well as the appearance of invasion, angiogenesis, and metastasis in certain types of cancer." (PMID 35807892, 2022). "VDR polymorphisms and in particular BsmI and TaqI may influence cancer outcome." (PMID 33917614, 2021). "Previous studies have provided evidence that women with low serum 25-OH-D3 levels and high tissue levels of VDR and ERα gene expression not only had increased risk for breast cancer but also had worsened cancer prognosis and decreased survival rates as compared to patients with other cancers." (PMID 33803480, 2021). "Indeed, the presence of VDR in cancer cells is essential for the activity of calcitriol and high VDR expression has been associated with improved prognosis and reduced risk of death from cancer." (PMID 33133014, 2020). "In addition, VDR KO mice manifest some of the health problems observed during the human aging process such as infertility, muscle atrophy, immune deficiency, osteoporosis and sensitivity to cancer." (PMID 32554862, 2020). "Therefore, the decreased sensitivity to calcitriol may be caused by epigenetic corruption of the VDR in cancer cell lines." (PMID 33291213, 2020). "Future studies should aim to evaluate associations between VDR expression and survival in patients with advanced disease as has been demonstrated for other cancer sites, however given the limited expected survival within this group of patients it may be difficult to detect significant benefits." (PMID 30344947, 2018).
cancer (continued). "Similarly, a meta-analysis of studies evaluating circulating vitamin D levels, functionally relevant vitamin D receptor genetic variants and variants within vitamin D pathway genes and cancer survival or disease progression showed a benefit of higher vitamin D levels on survival." (PMID 29315215, 2018). "Several VDR gene polymorphisms have been identified that may influence cancer risk." (PMID 30157901, 2018). "Therefore, it is hypothesised that not only vitamin D status but also expression and structure of VDR determine molecular actions, and can potentially modify cancer risk and survival." (PMID 28301870, 2017). "This creates a positive feedback loop and contributes to chemopreventive mechanism of vitamin D. Thus, genotyping the patients with cancer for mutations at serine residues 208/222 of VDR might be used for exclusion of these patients from vitamin D-directed anti-cancer therapy." (PMID 28427151, 2017). "VDR is located on the long arm of chromosome 12q12-q14, and several single nucleotide polymorphisms (SNPs) within the gene have been identified that may influence cancer risk." (PMID 27174575, 2016). "The considerable host of actions performed by PPARG can be compared to those of vitamin D and VDR, which has been implicated in neurologic disorders, autoimmune pathologies, cardiovascular disease, diabetes mellitus, psoriasis or infectious disease, and, above all of what is mentioned, cancer." (PMID 27579030, 2016). "Furthermore, the observed anti-cancer effects associated with vitamin D could, to some extent, be a result of a positive feedback mechanism on the production of VDR and/or CaSR by colorectal mucosa." (PMID 26205949, 2015). "Notably, variation in VDR gene has been implicated in many carcinomas." (PMID 25945350, 2015). "To date, the importance of the role of VDR polymorphisms in carcinogenesis is unclear, but when analysed with additional factors like VDR haplotype combinations, vitamin D serum levels and other confounders, polymorphisms have been shown to play an important factor in cancer prognosis." (PMID 25255691, 2014). "However, the relationship between VDR polymorphisms and these two specific cancers remains a controversial hypothesis, and consequently needs further confirmation via clinical research together with genetic investigations." (PMID 24297042, 2014). "Thus, the altered biological activities of this VDR variant may lead to susceptibility to various types of cancer." (PMID 23826116, 2013). "Moreover, VDR FokI and BsmI single nucleotide polymorphisms (SNPs) might modulate the risk of breast, skin, and prostate cancer as well as other cancer sites." (PMID 22242137, 2011). "Therefore, in a sunny region such as Spain, the effect of VDR polymorphisms on cancer risk may be more apparent than in other Caucasian populations." (PMID 19105801, 2008). "Despite promising preclinical results, most synthetic VDR agonists fail to show efficacy in cancer therapy due to calcemic toxicity." (PMID 41828612, 2026). "VDR-mediated signaling prevents cancer development and improves prognosis, making it an appealing target for therapy." (PMID 41901339, 2026). "We determined the moderately positive statistically significant association between the cancer grade and CD44 (r = 0.3930, p < 0.0001), VDR (r = 0.4170, p < 0.0001), and FIGO stage (0.3875, p < 0.0001)." (PMID 40332380, 2025). "This is probably because these are all patients with PCa and would expectedly have low serum vitamin D activity inasmuch as a review by Merchan et al28 postulates that in late-stage cancers, the vitamin D/VDR system is probably less functional." (PMID 39963174, 2025). "Polymorphisms in the vitamin D receptor (VDR) can influence inflammation, fibrosis progression and cancer susceptibility." (PMID 41561541, 2025). "In human studies, VD levels and the expression of VD receptor (VDR) target genes correlate with improved cancer prognoses and enhanced efficacy of ICIs." (PMID 40806182, 2025).
cancer (continued). "Combination therapies have been used to overcome these limitations in cancer types with reduced expression of VDR." (PMID 40071065, 2025). "Due to its role in inhibiting cancer cell proliferation and promoting apoptosis, VDR can also serve as a potential therapeutic target for various types of cancer, including ATC." (PMID 40071065, 2025). "Calcitriol significantly upregulated VDR expression in all three tested cancer cell lines: Panc02 (p < 0.008), PANC-1 (p < 0.007), and 4T1 (p < 0.002)." (PMID 41282147, 2025). "VD demonstrates synergistic potential in cancer immunotherapy, primarily mediated through its interaction with the VDR." (PMID 40806182, 2025). "VDR has been reported in several cancer types as well, such as breast cancer, colon cancer, and leukemia." (PMID 40071065, 2025). "Various transcription factors such as SNAIL1 and SNAIL2, drivers of epithelial–mesenchymal transition (EMT), directly repress VDR expression, preventing the action of calcitriol in late stages of cancer." (PMID 41301826, 2025). "SNPs in the VDR (Vitamin D Receptor) gene have been reported to affect the survival rate of several cancers." (PMID 40869905, 2025). "Expression of VDR is high in normal intestinal epithelium and plays a key role in mediating the anti-cancer effects of vitamin D42." (PMID 41444742, 2025). "On the other hand, in tumor tissue, VDR expression is typically downregulated, which can impair the cancer cells' ability to bind to vitamin D and allow them to bypass checkpoints, encouraging cell proliferation and tumor progression." (PMID 40071065, 2025). "In CRC, VDR helps regulate the immune response and inflammation, which are key factors in cancer progression." (PMID 40791849, 2025). "Though proliferative cancer cell lines have various forms of pro-estrus transforming growth factor receptor localization, mitochondrial VDR is ligand-independent." (PMID 40077673, 2025). "Interactions between 1,25(OH)2D] and vitamin D receptor (VDR) occur in virtually every cell in the body, including cancer cells." (PMID 40732958, 2025). "The varying expression levels of VDR are also apparent in ATC tissue, as some report loss of VDR expression is the majority of their samples, but others have confirmed VDR expression in ATC-derived cancer stem cell tissue." (PMID 40071065, 2025). "Vitamin D shows synergistic potential in cancer immunotherapy, primarily via the VDR, which is widely expressed in T cells, dendritic cells, and macrophages." (PMID 41041128, 2025). "From a clinical perspective, VDR is widely expressed in various tumor tissues and plays a role in cancer development, although its expression varies among cancer types." (PMID 40872626, 2025). "It has been demonstrated that vitamin D signaling, mediated by VDR, can slow the proliferation of cancer cells, as confirmed by in vitro studies and animal models." (PMID 40362574, 2025). "The link between VDR and cancer emanated from the “inconclusive” antineoplastic effects of the natural substrate 1α,25-dihydroxy vitamin D3." (PMID 38318147, 2024). "However, while our findings suggest that these particular polymorphisms may not be significant risk factors for CRC in this cohort, future research should explore the broader implications of VDR polymorphisms, particularly in relation to cancer progression, recurrence, survival, and drug resistance." (PMID 39451780, 2024). "Tumor microenvironment is thought to be potential therapeutic target in many types of cancers in recent years, thus we analyzed the correlation between VDR expression and tumor microenvironment." (PMID 38639057, 2024). "Since VDR is widely expressed in human tissues, we next examined VDR expression in various types of cancers." (PMID 38639057, 2024). "In this study, the expression of VDR was investigated in numerous cancers and normal tissue samples using TIMER 2.0." (PMID 39268267, 2024).